TNF (tumor necrosis factor)
Diseases named in the same sentence as TNF in open-access papers (continued):
Sharing a sentence is not in itself a finding about the gene and the disease.
atrial fibrillation (68 papers, 2010 to 2026). A disorder characterized by an electrocardiographic finding of a supraventricular arrhythmia characterized by the replacement of consistent P waves by rapid oscillations or fibrillatory waves that vary in size, shape and timing and are accompanied by an irregular ventricular response. "Post-exercise, phosphorylation levels of downstream factors in the TNFα signaling pathway, such as NF-κB, increase, leading to atrial fibrosis and heightened susceptibility to atrial fibrillation (AF)." (PMID 40658689, 2025). "Also post-operative atrial fibrillation (POAF) has determined correlation with inflammatory processes associated with elevated TNF-α and IL-6 levels." (PMID 41574188, 2025). "TNF-α is an inflammatory mediator associated with atrial fibrillation." (PMID 40786071, 2025). "In addition, both hs-CRP and TNF-a have been shown to upregulate angiotensin type 1 receptors in vascular and cardiac fibroblasts, underlying the correlation between inflammation and atrial fibrillation." (PMID 39274304, 2024). "In addition, there has been found the association of RDW with oxidative stress in animal models, with blood TNF-alpha levels in critically ill patients, and with atrial fibrillation and its risk of complications and mortality." (PMID 32224967, 2020). "In our study in hypertensive patients with diastolic HF, carrying allele A in TNF-308 G/A rs1800629 polymorphism was significantly associated with higher incidence of paroxysmal atrial fibrillation and could also play a role in the alteration of blood pressure." (PMID 28827564, 2017). "NF-κB and TNF-α protein expression, along with inflammatory cell infiltration, were significantly elevated in the atrial tissues of patients with atrial fibrillation and in rats." (PMID 40098617, 2025). "Circulating biomarkers reveal a steady increase in pro-inflammatory cytokines (IL-6, IL-17, TNF-α) and a decrease in regulatory T-cell fractions in non-paroxysmal atrial fibrillation." (PMID 41156185, 2025). "Metformin has been identified as a repurposed drug for atrial fibrillation (AF), a disease characterized by high serum TGFβ and TNFα." (PMID 41152229, 2025). "Research has also demonstrated that TNF has a role in the development of atrial fibrillation by increasing the arrhythmogenicity of the pulmonary veins and causing an imbalance in calcium homeostasis." (PMID 41294894, 2025). "In the atrial fibrillation group of patients, TNF levels were significantly correlated with left atrial volume." (PMID 38396488, 2024). "It has been reported in previous studies that serum levels of pro-inflammatory cytokines such as hs-CRP and TNF-α is closely related to the pathogenesis of atrial fibrillation (AF) and compelling evidence shows that there is a link between inflammation and AF." (PMID 35148750, 2022). "Regarding TNF-α, some previous studies revealed that ALA decreased TNF-α level in type-1 diabetic patients with subclinical left ventricular dysfunction and in patients with atrial fibrillation." (PMID 35596774, 2022). "Multiple animal studies have shown reductions in atrial fibrillation with the use of TNF and TNF‐receptor blockers." (PMID 33664879, 2021). "In clinical studies, needle-based auricular VNS decreased serum IL-6 in patients with lung lobectomy; taVNS decreased serum TNF-α in patients with paroxysmal atrial fibrillation." (PMID 34138761, 2021). "Pro‐inflammatory cytokines, such as IL‐6 and TNF‐α, are considered key mediators of inflammation‐related atrial fibrillation." (PMID 32441464, 2020). "Ang ІІ concentration, along with TGF-β1 and tumor necrosis factor-α levels, was slightly increased in plasma of patients with atrial fibrillation." (PMID 28871102, 2017). "Patients with atrial fibrillation demonstrate evidence of inflammation, with elevated levels of inflammatory markers, including C-reactive protein, interleukin-6, and tumor necrosis factor-α." (PMID 21896397, 2012).
atrial fibrillation (continued). "Elevation of tumor necrosis factor and IL-6 occurs one to two days following intravenous administration of bisphosphonates and can increase the incidence of atrial fibrillation." (PMID 21838908, 2011). "Likewise, venous blood samples were used to determine the proinflammatory cytokine levels such as TNF‐α and IL‐6, and the results showed an increase in the atrial fibrillation group." (PMID 32808366, 2021). "Furthermore, tVNS reduced atrial fibrillation in patients with paroxysmal atrial fibrillation (PAF) and reduced plasma levels of the inflammatory cytokine TNFα, which is associated with chronic increases in inflammation with ageing." (PMID 31358702, 2019). "However, there is humble evidence that inflammation, besides TNF-alpha, influences cardiac ion channels, atrial fibrillation and heart rate." (PMID 24770373, 2014). "Inflammatory mediators produced by mononuclear macrophages, such as TNF-α and IL-6, promote atrial myocyte degeneration and fibrosis and slow conduction, thereby contributing to both structural and electrical remodeling that can initiate and sustain atrial fibrillation." (PMID 41608286, 2026). "The increased mRNA expressions of classic inflammatory factors (i.e., interleukin-1 beta, interleukin 6, and tumor necrosis factor-alpha) in AF(+)thrombus(+) group further validated the correlation between inflammation and thrombi in atrial fibrillation." (PMID 29595637, 2018). "Plasma levels of inflammatory cytokines of IL‐2, IL‐4, IL‐10, TNF, and IFN‐γ were reduced upon rivaroxaban treatment compared to warfarin in atrial fibrillation patients, with levels still slightly higher than controls." (PMID 40292918, 2025). "Studies of humans with atrial fibrillation identified an activation of inflammatory factors such as IL6 and TNFα, and an increased number of CD3-positive T cells." (PMID 36928240, 2023). "To clarify the correlation between inflammation and thrombosis in atrial fibrillation, we detected the mRNA expressions of classic inflammatory molecules (i.e., IL-1β, interleukin-1 beta; IL-6, interleukin 6; TNF-α, tumor necrosis factor-alpha)." (PMID 29595637, 2018). "Elevated levels of CXCL8, CCL11, CCL2, CXCL10, IL-1β, IL-6, TNF-α, IFN-γ, IL-17, IL-1Ra, IL-4, IL-9, FGF-basic, PDGF, G-CSF, and GM-CSF were observed in the Atrial fibrillation patient, in contrast to uninfected controls." (PMID 29370812, 2018). "Univariate logistic regression showed that atrial fibrillation, CKD stages 1–3, LAVI < 39 mL/m2, E/e` < 17, hs-CRP < 6.1 mg/L, TNF-alpha < 3.7 ng/mL, NT-proBNP < 1540 pmol/mL, sST2 < 31 ng/mL, galectin-3 < 28 ng/mL, and irisin > 10.8 ng/mL were associated with improved LVEF in individuals with HF." (PMID 40299414, 2025). "Furthermore, increased levels of CCL5, IL-1β, TNF-α, IFN-γ, IL-9, G-CSF, and GM-CSF were observed only in the atrial fibrillation patient, when compared to other Zika patients." (PMID 29370812, 2018). "In general, the results revealed that the ZIKV-infected patient with atrial fibrillation presented a typical serum biomarker storm already reported for ZIKV-infected patients, with a more prominent pro-inflammatory status mediated by CCL5, IL-1β, TNF-α, and IFN-γ." (PMID 29370812, 2018). "Additionally, the mRNA expression of TNFα and TGF-β1, representative inflammatory markers, was highly increased in patients with atrial fibrillation, and after DCCV treatment, their expression returned to normal levels." (PMID 28871102, 2017). "“Normal” values are age and disease state-dependent, but for perspective, the case-matched controls with no arrhythmias in our atrial fibrillation study had mean DROMS 310 Carr units, Eh CySH −77 mV, Eh GSH −154 mV, IL-1β 0.4 pg/mL, IL-6 3.9 pg/mL, TNFα 5.5 pg/mL, and hsCRP 3.6 μg/mL." (PMID 20369058, 2010).
joint disease (68 papers, 2005 to 2025). "While TNF-α is mostly associated with bone and joint disease in mucopolysaccharidoses, increasing evidence implicates IL-1 as a main effector of innate immunity in the central nervous system." (PMID 35216110, 2022). "While TNF-α is mostly associated with bone and joint disease in MPSs, IL-1 seems to be more involved in CNS inflammation." (PMID 35216110, 2022). "Among the inflammatory mediators associated with joint diseases, tumor necrosis factor alpha (TNF-α) is well established as a key mediator in the progression of cartilage degeneration." (PMID 15642133, 2005). "Moreover, markers associated with low inflammation levels, such as TNF-α, IL-6, and IL-1β, are under extensive investigation and are proposed as discriminators between OA and other joint disorders characterized by a severe inflammatory component." (PMID 38785519, 2024). "Additionally, multiple AI’s have increased levels of certain inflammatory markers such as TNF-a, IL-6, and IL-17 that have been shown to contribute to arthropathy and are also linked to increased levels of gut dysbiosis." (PMID 37371676, 2023). "In fact, worsening of joint disease was associated with a marked increase of local proinflammatory cytokines (IL-6, IL-1β, and TNF-α) responsible for articular damage, together with sustained levels of monokines and a consequent enhanced inflammatory cell influx." (PMID 19606256, 2009). "Intriguingly, the combination of an anti-TNF monoclonal antibody to neutralize TNF plus etanercept, which additionally neutralizes LTα3, was effective in a case report of a patient with severe HLA-B27–associated arthropathy who had failed treatment with either agent alone." (PMID 35077396, 2022). "However, the suppression of joint disease with anti-TNFα therapy in RA patients may be associated with an early reduced risk of MI." (PMID 17763428, 2007). "Conversely, at W0, TNFα levels correlated negatively with joint disease indices, DAPSA and DAS28-CRP, with higher levels in those with less active disease (rs=0.48, p=0.034 and rs=0.45, p=0.047, respectively).." (PMID 40261944, 2025). "Dose intensification was applied to patients on anti-TNF therapy and active intestinal disease and/or arthropathy, either empirically or guided by subtherapeutic trough levels." (PMID 40004889, 2025). "Tumor necrosis factor alpha (TNFα), as a key pro-inflammatory cytokine, plays a central role in joint diseases." (PMID 39409134, 2024). "Studies in animal models of several different MPS types have identified TNF-α and its transcriptional regulators as important effectors mediating inflammation in bone and joint disease." (PMID 38173710, 2024). "During surgery three patients required a protective stoma placement: two patients for an intraoperative abscess and one patient for a severe digestive and joint disease requiring heavy immunosuppressive drugs (steroids and anti-TNF and methotrexate)." (PMID 36882155, 2024). "For instance, clinical RA is not only more prevalent in females compared to males, but females tend to also experience more severe erosive joint disease, lower rates of remission, and increased functional decline, similarly demonstrated in the TNF-Tg mice." (PMID 36732826, 2023). "The elevated levels of IL-1β, IL-6, and TNF-α, as well as of MMPs, found in the SF of both OA and RA patients confirmed their important role in the pathogenesis of these joint diseases." (PMID 35955467, 2022). "Degradation of the osteoarticular system in the course of arthropathy is connected with hypersecretion of proinflammatory cytokines, including tumor necrosis factor alpha (TNF-α), interleukin (IL) 1β, or IL-6." (PMID 36079004, 2022). "Both infliximab and adalimumab, targeting TNFα, are potential candidates for bone and joint disease." (PMID 35216110, 2022). "The production of inflammatory mediators like IL-6 and TNF-α show a critical role in the advancement of joint disorder, bone distortion, pain, and tenderness." (PMID 33919084, 2021).
joint disease (continued). "Tumor necrosis factor α (TNF-α) and Interleukin 1β (IL-1β) are potent activators of intra-articular inflammatory pathways and synovial concentrations correlate with joint disease in humans and horses." (PMID 34901249, 2021). "Inappropriate release of TNF-α was shown to contribute to arthropathy development following intra-articular bleeding in hemophilic mice." (PMID 31261789, 2019). "Aside from tumor necrosis factor (TNF), interleukin-17A (IL-17A) has been identified as a key cytokine in psoriatic skin and joint disease." (PMID 30053825, 2018). "Interestingly, there is link between gut and joint disease as they often co-incide and share certain aspects of the pathogenesis such as established genetic risk factors, a critical role for pro-inflammatory cytokines, such as TNF-α, IL-23, and IL-17 and therapeutic susceptibility." (PMID 30008717, 2018). "Pain management therapies as well as drugs with anti-inflammatory potential (e.g anti-TNF based therapy) have been shown to significantly improve motor function and balancing on rotarod test in animal models of joint diseases." (PMID 27333300, 2016). "We describe two cases of patients who were given TNF-α antagonists to treat long-standing joint disease, who then experienced the involvement of several organs leading to the diagnosis of WD." (PMID 26215452, 2015). "Further research is needed to understand variations in responses to TNF antagonists, not only for individual patients, but also with respect to destructive versus proliferative joint disease in PsA." (PMID 20537151, 2010). "For example, reductions in circulating levels of pro-inflammatory markers such as interleukins and tumor necrosis factor-alpha (TNF-α) have been observed in response to probiotic supplementation, both of which are known to play a role in bone and joint disease." (PMID 40564317, 2025). "In vitro and in vivo studies validated the cytokine, tumor necrosis factor (TNF)-α, as multifunctional key player in the pathophysiology of joint diseases such as OA, since its promotion of numerous further cytokines and enzymes activates an almost unstoppable pro-inflammatory cycle." (PMID 38500879, 2024). "However, in joint diseases like RA, pro-inflammatory cytokines released by the synovium, including Interleukin (IL)-1β, -6, -17, and Tumor Necrosis Factor (TNF)-α, contribute to chondrocyte death and matrix disruption." (PMID 37371936, 2023). "Herein, we demonstrate a significant increase in IgG2b class-switching and accumulation of plasma cells in Advanced vs Early PLN sinuses, which corresponds to the enigmatic process of lymph node collapse and severe exacerbation of arthritic flare in late-stages of TNF-Tg joint disease." (PMID 37691918, 2023). "We tested the hypothesis that alpha smooth muscle actin (αSMA)+ PLV-LMC coverage decreases with severe inflammatory-erosive arthritis, and is recovered by anti-TNF therapy facilitated by increased PLV-LMC turnover during amelioration of joint disease." (PMID 35882971, 2022). "Previous studies in the tumor necrosis factor transgenic (TNF-Tg) mouse model of RA demonstrated that these PLVs are able to initially drain the inflamed joint effectively leading to dramatic PLN expansion with limited joint disease." (PMID 35255954, 2022). "Importantly, treatment with a selective iNOS inhibitor in vivo was sufficient to recover PLV contraction frequency in TNF-Tg mice, and TNF-Tg x iNOS−/− mice exhibited reduced joint disease at early time points in females with accelerated arthritic progression." (PMID 35255954, 2022). "Besides, we also found that TRAP was positively correlated with IL-1 β, IL-6, TNF-α, and type II collagen in joint effusion." (PMID 33706812, 2021). "The disease first manifests as arthralgia and/or arthropathy that usually precede the diagnosis by years, and which may push clinicians to prescribe Tumor necrosis factor inhibitors (TNFI) to treat unexplained arthralgia." (PMID 34093562, 2021).
joint disease (continued). "IL-1β and TNF are major mediators in various joint disorders, not only through their direct effects, but also via inducing the release and activation of other inflammatory mediators, being crucial in the initiation and/or perpetuation of an inflammatory insult." (PMID 31860662, 2019). "We corroborated these results by measuring cytokine concentrations in synovial lavage fluid and in plasma samples and show that TRPC5 deletion or antagonism increased the local secretion of a number of critical pro-inflammatory cytokines (eg, TNFα, IL-1β) with an established role in joint disease." (PMID 27165180, 2017). "Also, pro-inflammatory cytokines such as TNF-alpha and IL-1 beta that play an important role in joint diseases are central inducers of joint pain and tissue destruction." (PMID 27333300, 2016). "New therapeutic strategies based around the use of anti-inflammatory drugs (e.g. anti-TNF-alpha antibodies, pentosan polysulfate) for the treatment of joint disease may be promising approaches." (PMID 27392569, 2016). "Given previous work suggesting the higher efficacy of anti-TNFα compared to anti-IL12/23 therapy for SpA symptoms, further work is needed to define the potential medication-specific impact and to assess longitudinal tracking of specific strains associated with joint disease activity." (PMID 39949039, 2025). "It remains possible that unmeasured symptoms related to bone and joint disease, such as pain, may be the dominant feature that ultimately reduces activity in TNF-Tg mice and may eventually negate the early beneficial effects of wheel running on increasing aerated lung volumes." (PMID 36732826, 2023). "However, while these studies strongly implicate intrinsic PLV defects in the progression and flare of joint disease in TNF-Tg mice, in vivo studies cannot isolate PLV function independent of the upstream inflammation in the arthritic joint, and potential immune reactions in the efferent PLN." (PMID 34646163, 2021). "Finally, this study motivates further investigation into the role of the TNF-α-TSG-6-HC-HA axis in joint disease, including how TSG-6 and HC-HA may affect infiltration, activation, and residence times of inflammatory cells and synovial fluid lubrication." (PMID 34416923, 2021). "However, by using a unique combination of cellular and imaging data, we show that the subset of patients requiring continuation of anti-TNF therapy to maintain remission of their joint disease had increased arterial wall and cellular inflammation compared to those using DMARDs only." (PMID 27209093, 2016). "Dose optimization of anti-TNF agents was guided by either the assessment of anti-TNF trough and antibody levels or empirically in patients with active IBD and/or active arthropathy." (PMID 40004889, 2025). "Overall, these findings suggest the implication of the TLR4/TNF-α signalling pathway in MPS bone and joint disease, and the TLR4/IL-1 in neurodegeneration." (PMID 35216110, 2022). "Several inflammatory mediators secreted from adipose tissue, including interleukin-1α (IL-1α), IL-1β, IL-6, IL-10, tumor necrosis factor-α (TNF-α), monocyte chemotactic protein-1 (MCP1) and prostaglandin E2, have been shown to be involved in joint diseases." (PMID 25996876, 2015). "However, TNF inhibitors cannot be considered completely ineffective for RPE treatment, as some patients exhibit improved joint disease activity after TNF inhibitor therapy." (PMID 39744302, 2024). "A current model for the findings in MPS joint disease hypothesizes that accumulated glycosaminoglycans (GAG) bind to and activate toll-like receptor 4 (TLR4) leading to expression of TNF-α and matrix metalloproteinases." (PMID 38173710, 2024). "Starting at 8 years of age, F2:II-4 experienced the onset of a non-destructive, deforming arthropathy which has been refractory to broad-spectrum immunosuppression, anti-IL-1 receptor, anti-IL-1β and anti-TNFα therapies." (PMID 29259162, 2017).